C6 (complement C6)
Description:
Component of the membrane attack complex (MAC), a multiprotein complex activated by the complement cascade, which inserts into a target cell membrane and forms a pore, leading to target cell membrane rupture and cell lysis. The MAC is initiated by proteolytic cleavage of C5 into complement C5b in response to the classical, alternative, lectin and GZMK complement pathways. The complement pathways consist in a cascade of proteins that leads to phagocytosis and breakdown of pathogens and signaling that strengthens the adaptive immune system. Together with component C5b, involved in MAC complex assembly: complement C5b and C6 associate with the outer leaflet of target cell membrane, reducing the energy for membrane bending.
Tractability: Small molecule: a structure with a bound ligand is known. Antibody: UniProt places it where antibodies can reach, with high confidence; its Gene Ontology location is reachable by antibodies, with high confidence; UniProt predicts a signal peptide or a membrane-spanning region. PROTAC: its protein half-life has been measured.
Gene: Protein-coding gene on chromosome 5 (41,140,236 to 41,261,561, reverse strand). Ensembl gene ENSG00000039537.
Subcellular location: Secreted; Target cell membrane
Pathways (Reactome):
Immune System: Regulation of Complement cascade; Terminal pathway of complement
Gene Ontology:
Molecular function: protein binding; wide pore channel activity
Biological process: complement activation; complement activation, GZMK pathway; killing of cells of another organism; positive regulation of immune response; immune response; transmembrane transport
Cellular component: extracellular exosome; extracellular region; membrane attack complex; other organism cell membrane; plasma membrane
Genetic constraint (gnomAD): Loss-of-function variants: 93 observed, 109.64 expected, observed/expected ratio (o/e) 0.85, 90% interval 0.72 to 1.01. The upper end of that interval is the gene's LOEUF score, 1.01, which puts it in group 4 of 6, group 1 being the genes least tolerant of losing a copy. Missense variants: 1,106 observed, 1,074.8 expected, observed/expected ratio (o/e) 1.03, 90% interval 0.98 to 1.08. Synonymous variants: 404 observed, 379 expected, observed/expected ratio (o/e) 1.07, 90% interval 0.98 to 1.16.
Homologues: Orthologues: chimpanzee C6 (99% identical), macaque C6 (96% identical), dog C6 (84% identical), rabbit C6 (80% identical), rat C6 (79% identical), pig C6 (76% identical), mouse C6 (75% identical), guinea pig C6 (75% identical), tropical clawed frog c6.2 (54% identical), zebrafish c6.2 (44% identical), zebrafish c6.1 (41% identical). Paralogues in human: C7 (29% identical), C8A (19% identical), CSMD3 (18% identical), CSMD2 (18% identical), C8B (18% identical), CSMD1 (17% identical), SVEP1 (15% identical), C9 (15% identical), PAPPA (14% identical), CR1 (13% identical), PAPPA2 (13% identical), CFH (13% identical), and 27 more.
Diseases named in the same sentence as C6 in open-access papers:
C6 is named in the same sentence as 64 diseases in open-access papers, as found by Europe PMC text mining. Sharing a sentence is not in itself a finding about the gene and the disease. The quoted sentences say what the papers report.
complement deficiencies (4 papers, 2020 to 2024). "While complement deficiency is associated with recurrent infections, glomerulonephritis, and inflammatory disorders affecting the kidney and eyes, inherited deficiency of C6 has shown to delay the onset of proteinuria and improve renal function in a rat model." (PMID 38762513, 2024). "Complement deficiency was represented by a pathogenic frameshift variant (p.Gln380SerfsTer7) in the C6 gene, causing C6 deficiency (OMIM #612446)." (PMID 37592284, 2023). "Unlike previous cases, the patient we described in the present report had an undetectable C6 level; thus, the complement deficiency in our case was appropriately designated C6Q0." (PMID 32481330, 2020). "Primary complement deficiencies in this cohort included C1q deficiency (n = 3), C2 deficiency (n = 11), C6 deficiency (n = 3), and C8 deficiency (n = 1)." (PMID 32972440, 2020). "A rare pathogenic SNV was found in the C6 gene related to complement deficiencies." (PMID 37592284, 2023).
COVID-19 (4 papers, 2021 to 2025). A disease caused by infection with severe acute respiratory syndrome coronavirus 2. "Our analysis showed that Complement C1q [P02746, P02746] and Complement C6 [P13671] proteins decreased in the post-COVID-19 group compared to the uninfected." (PMID 36077551, 2022). "LGALS3BP abundance in COVID-19 patients closely correlated with proteins and regulators of the complement cascade (C6, C9, C4BPA, and C4BPB)." (PMID 34099652, 2021).
Lyme disease (3 papers, 2021 to 2023). Lyme disease (named after the towns in the USA where the disease was first identified) is a bacterial infection caused by Borrelia burgdorferi. "Intensive research over the last 20 years has identified broadly recognized in-vivo and in-vitro expressed antigens that generate antibody responses in most patients with Lyme disease (e.g., VlsE, C6, DbpA, BBK32, FlaB, and OspC)." (PMID 34499659, 2021). "Further, current standard diagnostic assays of Lyme disease, targeting the anti-VlsE or anti-C6 antibodies, do not distinguish between active and past infections." (PMID 36150043, 2022). "The Newly Diagnosed Lyme Disease Patient MENSA and serum samples obtained during 6–18 DPSO were assessed for anti-C6 and anti-pepC10 antibody levels." (PMID 37922270, 2023).
meningococcal disease (3 papers, 2018 to 2024). "C6 deficiency is also a high-risk factor for Neisseria meningitidis infection." (PMID 39823049, 2024). "It remains to be demonstrated whether treatment with a C6 inhibitor will cause less risk of meningococcal infections due to the extra anti-microbial protection provided by the C5a-related anaphylactic mechanism." (PMID 29724241, 2018).
viral infection (3 papers, 2011 to 2022). "We showed that C6 is expressed early during viral infection and localizes in the cytoplasm of infected cells." (PMID 21909386, 2011). "C6 is a 18.2 kDa protein, which is expressed early during virus infection and localizes to the cytoplasm of infected cells." (PMID 21909386, 2011).
gastric cancer (2 papers, 2022 to 2026). A primary or metastatic malignant neoplasm involving the stomach. "In the present study, we analyzed the DNA sequencing data of 229 patients from the TCGA-STAD project and identified five potential driver genes (CCDC169-SOHLH2, TTN, KNL1, C6, NRXN1) whose mutations were negatively associated with gastric cancer recurrence (p < 0.01)." (PMID 35187167, 2022). "Second, while SERPINE1 was functionally characterized, the roles of other signature components (e.g., C6, GRP, GCG) in gastric cancer remain unclear and merit further investigation." (PMID 41551463, 2026).
glaucoma (2 papers, 2017 to 2024). Increased pressure in the eyeball due to obstruction of the outflow of aqueous humor. "We quantified the majority of key proteins associated with classical complement pathway, such as C1q, C1s, C1r, C4a, C4b, C3, C5, C6, C7, C8a, C8b, C8g and C9, as up-regulated in glaucoma condition for both vitreous and retinal tissues when compared to the controls." (PMID 28978942, 2017).
lung carcinoma (2 papers, 2019 to 2022). "However, there are few studies on the functions of complement C6 in lung cancer." (PMID 35581376, 2022).
periodontitis (2 papers, 2023 to 2025). An acute or chronic inflammatory process that affects the tissues that surround and support the teeth. "Genetic analysis of saliva sEVs showed that innate immune response proteins were considerably enriched in patients with severe periodontitis, particularly the complement component 6 (C6)." (PMID 37114060, 2023).
Achalasia (1 paper, 2023). A disorder of esophageal motility characterized by the inability of the lower esophageal sphincter to relax during swallowing and by inadequate or lacking peristalsis in the lower half of the body of the esophagus. "In the current study, complement C1q, C1s, C2, C3, C4-A, C4-B, C5, C6, and C9 were all upregulated in the achalasia group." (PMID 37324545, 2023).
Arthritis (1 paper, 2020). Inflammation of a joint. "Furthermore, C6 deficiency has been implicated in decreased hemolytic activity and susceptibility to collagen antibody-induced lesions in arthritis." (PMID 32528245, 2020).
bladder cancer (1 paper, 2020). "Validation for complement C6 expression in an independent cohort demonstrated significant reduction in C6 protein levels in low grade bladder cancer patients when compared to healthy controls (p = 0.046) which is consistent with the 2D-DIGE protein expression data." (PMID 32620920, 2020).
breast carcinoma (1 paper, 2020). "In the absence of sPLA2, the IC50 of c6-RAR prodrug in MT-3 breast cancer cell line was 110 μM, while the IC50 of c6-RAR prodrug decreased to 10 μm after adding sPLA2, indicating that the prodrug was hydrolyzed into c6-RAR and Lyso-O-SPG by sPLA2, in response to phospholipase." (PMID 32887466, 2020).
cataract (1 paper, 2023). Partial or complete opacity of the crystalline lens of one or both eyes that decreases visual acuity and eventually results in blindness. "Within the male cohort, three complement proteins (CLU, C6, and CFH) were downregulated in POAG patients compared to those with cataracts." (PMID 37763167, 2023).
chronic kidney disease (1 paper, 2025). Impairment of the renal function secondary to chronic kidney damage persisting for three or more months. "Importantly, intrarenal complement gene expression (C1R, C1QB, C6, C9, C5, MASP2) predicts nonresponse to induction therapy, alluding to the potential pathogenic role of intrarenal complement gene expression in chronic kidney disease." (PMID 41031884, 2025).
cowpox (1 paper, 2024). A mild, eruptive skin disease of milk cows caused by cowpox virus, with lesions occurring principally on the udder and teats. "The antiviral activity of HDAC5 is antagonized by VACV protein C6 and orthologs from the orthopoxviruses cowpox, rabbitpox, camelpox, monkeypox, and variola." (PMID 38461415, 2024).
Crohn disease (1 paper, 2024). A gastrointestinal disorder characterized by chronic inflammation involving all layers of the intestinal wall, noncaseating granulomas affecting the intestinal wall and regional lymph nodes, and transmural fibrosis. "Other notable markers up-regulated selectively in CD submucosa/wall compared to control include IL36a, IL16, and complement C9, while C6 is selectively increased in mucosa, highlighting a potential and perhaps underappreciated role for complement in the pathogenesis of Crohn’s disease." (PMID 38791146, 2024).
deficiencies (1 paper, 2020). "Complete C6 deficiency (C6Q0) is a rare primary immunodeficiency leading to increased susceptibility to recurrent Neisseria infections." (PMID 32670577, 2020). "However, unlike C9 deficiency (the most common TCC deficiency in the oriental populations), C6 deficiencies have seldomly been reported in Asians, especially in Han Chinese." (PMID 32670577, 2020).
glioma (1 paper, 2022). A benign or malignant brain and spinal cord tumor that arises from glial cells (astrocytes, oligodendrocytes, ependymal cells). "Due to the malignant nature of gliomas, most of the patients in group 2 were also classified as immune C4 (lymphocyte depleted) subtype, while only a few were classified as C1 (wound healing) subtype and immune C6 (TGF-beta dominant) subtype." (PMID 36474171, 2022).
Listeria infection (1 paper, 2021). "Eight of these genes were similarly inhibited by Listeria infection in PMH: they encode (i) the activating enzyme C1S of the C1 complex, (ii) the central component C3, (iii) the membrane-attack proteins C6 and C8A, and (iv) four complement regulators (C1QTNF6, CFH, CFHR2, VTN)." (PMID 34858876, 2021).
lymphedema (1 paper, 2022). Excess fluid collection in tissues, causing swelling. "We found a striking depletion of the anti-inflammatory macrophages, i.e., the c6 LYVE1+ resident-like subpopulation, in the adipose tissues of lymphedema." (PMID 35725971, 2022). "The macrophage subpopulation c6 was dramatically reduced in SVF and the macrophage lineage under lymphedema." (PMID 35725971, 2022).
malnutrition (1 paper, 2014). Inadequate nutrition resulting from poor diet, malabsorption, or abnormal nutrient distribution. "Few studies assessed C6, C9, and factor B, and most found reduced levels in malnourished children, most so in oedematous malnutrition." (PMID 25153531, 2014).
meningitis (1 paper, 2023). A disorder characterized by acute inflammation of the meninges of the brain and/or spinal cord. "Notably, all four (100%) children presenting with both facial nerve palsy and meningitis, as well as all six (100%) patients with meningitis alone, exhibited positive antibody responses to the C6 antigen." (PMID 38066788, 2023).
Opportunistic infection (1 paper, 2024). An infection that is caused by a pathogen that would generally not be able to cause an infection in a host with a normal immune system. "Here, we report a very rare case of recurrent opportunistic infections in a non-HIV-infected patient combined with mutations in complement component C6 and nuclear factor kB subunit 1 (NFKB1)." (PMID 39823049, 2024).
osteoarthritis (1 paper, 2024). A noninflammatory degenerative joint disease occurring chiefly in older persons, characterized by degeneration of the articular cartilage, hypertrophy of bone at the margins and changes in the synovial membrane. "Further analysis revealed that the TK1 gene was upregulated in osteoarthritis, tenosynovial giant cell tumors, and synovial sarcoma, while the C6 gene was downregulated in these three diseases." (PMID 38549939, 2024). "Therefore, this study reveals potential shared molecular mechanisms between tenosynovial giant cell tumors and osteoarthritis, synovial sarcoma, particularly the differential expression of TK1 and C6 genes in these diseases may reveal shared pathological processes." (PMID 38549939, 2024).
schizophrenia (1 paper, 2022). A major psychotic disorder characterized by abnormalities in the perception or expression of reality. "Accompanying the metabolic disruption identified in patients with schizophrenia was an increase in several complement effector proteins, including C4a/b, C5, C6, C8a, and C9." (PMID 34741130, 2022).
Stroke (1 paper, 2020). Sudden impairment of blood flow to a part of the brain due to occlusion or rupture of an artery to the brain. "Specifically, elements of the alternative pathway of complement system and MAC proteins, i.e., CFI, C6, C8A, C8G, C9 were found to be activated but also undergoing regulation at 3 months post-stroke." (PMID 32849183, 2020).
infection (27 papers, 2010 to 2025). The state of being infected such as from the introduction of a foreign agent such as serum, vaccine, antigenic substance or organism. "Complement is a humoral factor of innate immunity and plays a crucial role in the fish immune response to pathogen infection, including C1q, C3, C5b, C6, C7, C8, C9, etc.." (PMID 41154820, 2025). "Our study shows how S. chrysophrii infection changes the abundance of several complement proteins (factor H, factor B, factor I, C1q, C3, C4, C5, C6, C7, C8), inducing an inhibition of the alternative pathway as the infection intensity increases." (PMID 36088326, 2022). "Here we show that VACV also induces the proteasomal degradation of HDAC4 during infection of several cell types and this requires protein C6, a virulence factor and multifunctional IFN antagonist." (PMID 31127039, 2019). "This is why researchers have explored the use of a variety of targets including VlsE and C6 expressed after infection, Osp C and Fla B expressed by the feeding tick to detect infection sooner." (PMID 28002488, 2016). "Not all animals, however, were spirochete-free, so the question of what facet of infection is indicated by anti-C6 antibody titers was brought to the fore." (PMID 22253822, 2012). "Using a polyclonal antiserum raised against C6 protein expressed in Escherichia coli, a 17-kDa C6 protein was detected starting from 2 h post infection, with continued expression at all time points thereafter." (PMID 21931555, 2011). "The expression of C6 protein during infection was investigated by infecting BSC-1 cells with VACV WR in the presence or absence of cytosine arabinoside (AraC), an inhibitor of viral DNA replication and hence intermediate and late protein expression." (PMID 21931555, 2011). "C6 is another VACV protein that is expressed early after infection in the cytoplasm." (PMID 38412044, 2024). "As many as 1180 genes were differentially expressed and the most down-regulated genes were further analyzed for their role in infection (a chitin deacetylase, a C6 TF, a laccase, two proteases, the succinate dehydrogenase MoSSADH, the acetyltransferase MoACT, and the thioredoxin MoTRX2)." (PMID 38252628, 2024). "Moreover, anti-VlsE and anti-C6 antibodies exhibit a dynamic response to infection, swiftly appearing in the patient’s serum shortly after infection, and typically diminishing following successful treatment." (PMID 38066788, 2023). "Although the C6 antigen represents a reliable tool for investigating the infection status of dogs, the exclusive use of this antigen in the SNAP 4dx test may miss other antibodies, such as those for OspC, that are present at other infection stages." (PMID 36986392, 2023). "It is possible that the C6 protein may have a repertoire of accessory functions which could serve to fine-tune crucial infection events occurring at different regions within the cell." (PMID 37220127, 2023). "In comparing the groups with and without infection, the SNPs most significantly associated with infection were located in complement genes, including C3, C5, C6, C7, C9 and MBL2 (P < 10−6)." (PMID 27063552, 2016). "Mutant viruses in which the C6L gene is deleted, or mutated so that the C6 protein is not expressed, replicated normally in cell culture but were attenuated in two in vivo models of infection compared to wild type and revertant controls." (PMID 21931555, 2011). "The increased amount of early C6 protein at 22 h post-infection compared to what is produced when viral DNA replication is inhibited by AraC, is probably due to enhanced stability of the protein after virus DNA synthesis and to the contribution of progeny virus." (PMID 21909386, 2011). "Also, C6 was detected in the presence of AraC confirming its expression prior to DNA replication and hence as an early protein during infection, consistent with previous data for C6L mRNA expression." (PMID 21931555, 2011).